AHR (aryl hydrocarbon receptor)
Diseases named in the same sentence as AHR in open-access papers (continued):
Sharing a sentence is not in itself a finding about the gene and the disease.
atopic dermatitis (continued). "AhR is a positive upstream of skin barrier proteins; thus, activating AhR is important for alleviating atopic dermatitis." (PMID 36983027, 2023). "Tapinarof, an AhR agonist, has been approved for the treatment of plaque psoriasis and atopic dermatitis." (PMID 37573390, 2023). "Bifidobacterium longum CCFM1029 reshaped the gut microbial composition in atopic dermatitis patients, and activated the AHR-mediated immune response, alleviating related symptoms." (PMID 37942478, 2023). "Tapinarof and other high-affinity AHR (the aryl hydrocarbon receptor) agonists are currently being studied as promising candidates for new topical treatment of atopic dermatitis by enhancing FLG expression." (PMID 36904070, 2023). "According to a previous study, AhR is involved in mediating the effects of antioxidant phytochemicals in atopic dermatitis." (PMID 35625824, 2022). "In contrast, transgenic mice expressing a constitutively active AHR (AHR-CA) in the epidermis develop a phenotype that resembles atopic dermatitis (AD), including skin lesions with itching, skin inflammation, and immunological imbalance." (PMID 34437510, 2021). "Due to its broad roles, not limited to the intestinal health, the AhR is an emerging therapeutic target for the pharmacotherapy of several diseases, including atopic dermatitis, intestinal inflammation or cancer." (PMID 32316498, 2020). "Chronic exposure of skin to PAHs, such as DMBA, induces chronic keratinocyte-specific activation of the AhR, which leads to the symptoms of atopic dermatitis with chronic inflammation." (PMID 33178182, 2020). "Recently, topical agent with AHR agonistic activity has been reported to be beneficial for atopic dermatitis in clinical trial." (PMID 28892018, 2017). "As one of the available treatments for atopic dermatitis (AD), coal tar was found to promote epidermal differentiation by activating AhR." (PMID 27243009, 2016). "In the regulation of skin barrier function, human β-Defensin-3 can activate the autophagy pathway through the AhR signal and enhance the skin TJ barrier, ultimately alleviating atopic dermatitis-like inflammation, indicating a correlation between AhR and cellular autophagy function." (PMID 40665732, 2026). "In a model of MC903-induced atopic dermatitis, topical application or oral administration of microbiota-derived AhR ligand indole-3-aldehyde (IAId) reduced skin inflammation and type 2 responses, which was dependent on AhR." (PMID 37190854, 2023). "Diosmin activates AhR signaling pathways and alleviates atopic dermatitis." (PMID 36983027, 2023). "This showed that AhR is required for the action of tryptophan metabolites on atopic dermatitis." (PMID 36983027, 2023). "Whereas AHR has been involved in various skin disorders such as accelerated aging, skin carcinogenesis and inflammation AHR is also essential for skin barrier integrity and its activation has been reported to improve the skin barrier in atopic dermatitis." (PMID 37304256, 2023). "The aryl hydrocarbon receptors (AHR) agonist (tapinarof): For the treatment of psoriasis and atopic dermatitis, tapinarof, a new, first-in-class, small-molecule topical therapy aryl hydrocarbon receptor (AhR)-modulating drug, is currently undergoing clinical testing." (PMID 37965393, 2023). "Besides, an indole derivative IAId of microbiota-derived tryptophan metabolite exerts inverse effects on skin inflammation in atopic dermatitis patients by targeting AhR." (PMID 36601108, 2022). "Coal tar induces AhR-dependent skin barrier repair in atopic dermatitis." (PMID 35625824, 2022). "In a mouse model of atopic dermatitis (AD), the microbiota-derived tryptophan metabolite indole-3-aldehyde was shown to alleviate inflammation through binding and activation of the keratinocyte aryl hydrocarbon receptor (AhR)." (PMID 33468585, 2021).
atopic dermatitis (continued). "However, it is noteworthy that for the skin, drugs targeting AhR have been developed for the treatment of atopic dermatitis, an allergic disease characterized by a type 2 cytokine profile and recently described as elicited by pollutants through AhR." (PMID 33233810, 2020). "Recent clinical trials using Tapinarof cream, an AhR activator, have shown encouraging preliminary results in atopic dermatitis suggesting that AhR may represent a therapeutic target in allergic diseases." (PMID 33233810, 2020). "Beside its critical role in the development of chloracne, the hallmark of acute intoxication with dioxin-like chemicals in humans, AHR is involved in the pathogenesis of various other diseases and disorders of the skin, including atopic dermatitis, psoriasis, vitiligo, and cancer." (PMID 31795255, 2019). "The aryl hydrocarbon receptor (AhR) is a ligand-activated transcription factor that responds to multiple different environmental and metabolic stimuli to control transcriptional pathways of relevance to atopic eczema, including immunity and differentiation." (PMID 31641698, 2019). "Coordinated upregulation of skin barrier proteins by RCE via AHR may be beneficial in the management of barrier-disrupted inflammatory skin diseases such as atopic dermatitis." (PMID 29866992, 2018). "Mice expressing a keratin 14–driven constitutively active AHR exhibit skin lesions with itching that are consistent with atopic dermatitis, and one study of Korean Vietnam veterans reported a statistically significant association between the incidence of eczema and Agent Orange exposure." (PMID 24904982, 2014). "Fortunately, an AhR agonist, Tapinarof cream 1%, has been approved in the USA to treat plaque psoriasis in adults, and is under investigation for the treatment of atopic dermatitis, indicating that the development of AhR agonists with fewer side effects could be achieved." (PMID 38635505, 2024). "A study found that gut-derived Bifidobacterium mediated tryptophan metabolism to attenuate atopic dermatitis via the gut-skin axis; thus, microbial metabolites from tryptophan may be the means by which Bifidobacteria alleviate atopic dermatitis via the aryl hydrocarbon receptor signaling pathway." (PMID 37737154, 2023). "Mechanistically, BaP can directly activate aryl hydrocarbon receptor (AhR), induce IL-33 expression and eosinophil infiltration in a mouse model of allergic airway inflammation, and elicit T-helper 2-driven pro-inflammatory responses in a mouse model of allergic dermatitis." (PMID 33936062, 2021). "Interestingly, while exposure to several AHR agonists may foster the development and progression of certain skin diseases, such as atopic dermatitis, similar agents are being used for decades to treat these diseases." (PMID 31795255, 2019). "Therefore, in this study, AhR was explored as an atopic dermatitis (AD)-regulating target of KF for AD regulation using in silico prediction, and pharmacological prediction and various AD-induced models confirmed that KF exhibited pharmacological activity through AhR regulation." (PMID 41229709, 2025). "For example, coal tar, used as a treatment for atopic dermatitis, has been reported to increase the expression of NQO1 and Filaggrin via AhR." (PMID 34884772, 2021). "Combined activation of SIRT1 and AhR/AKT improved skin barrier repair and the therapeutic effects of coal tar on atopic dermatitis." (PMID 27243009, 2016). "AhR and NAD+-dependent deacetylase Sirtuin 1 (SIRT1) were analyzed in different disorders such as human vascular senescence and atopic dermatitis." (PMID 27243009, 2016). "Tapinarof is a nonsteroidal, topical, aryl hydrocarbon receptor agonist approved for the treatment of atopic dermatitis (AD) in Japanese patients aged ≥12 years." (PMID 39676466, 2025).
atopic dermatitis (continued). "Additionally, in the context of atopic dermatitis, where intense chronic itch is also observed, ARTN is released in the epidermis of patients via the activation of the aryl hydrocarbon receptor (AhR) by particulate matter in air pollution." (PMID 32252363, 2020). "Tapinarof 1% cream is a first-in-class, non-steroidal aryl-hydrocarbon-receptor (AhR) agonist that received U.S. FDA approval in 2022 for adult plaque psoriasis and in 2024 for atopic dermatitis." (PMID 41451029, 2026).
glioblastoma (71 papers, 2010 to 2025). The most malignant astrocytic tumor (WHO grade IV). "In certain contexts, such as glioblastoma, AhR interacts with HIF-1α to control glycolysis, a hallmark of cancer cells." (PMID 41440753, 2025). "Initially, AHR expression was found in human glioblastoma tissues; therefore, AHR is likely associated with tumor progression via the activation of its signaling in glial cells." (PMID 40711040, 2025). "Patients with high AHR and kynurenine levels are associated with reduced overall survival from glioblastoma, perhaps through an immunosuppression mechanism." (PMID 37755265, 2023). "Kynurenine produced by glioblastoma cells activated AhR in tumor-associated macrophages and suppressed NF-κB activation." (PMID 36721094, 2023). "In glioblastoma, inhibition of AhR has been associated with activation of the CXCL12-CXCR4-MMP9 signaling pathway, involved in cell growth, invasion-migration, and cell proliferation." (PMID 33451095, 2021). "In glioblastoma, AhR may interact with HIF-1α to control glycolysis, a hallmark of cancer cell metabolism." (PMID 41440753, 2025). "Moreover, high AHR activity associated with reduced overall survival in the glioblastoma TCGA dataset." (PMID 34646367, 2021). "Furthermore, high activity of AhR in glioblastoma is associated with reduced overall survival, suggesting AhR might become a potential therapeutic target in some tumor settings." (PMID 37277776, 2023). "Rutaecarpine, another alkaloid from Evodia rutaecarpa, has been shown to inhibit U87 glioblastoma cell migration by activating the aryl hydrocarbon receptor (AhR) signaling pathway." (PMID 40286187, 2025). "Blocking AhR delays the progression of IDO/TDO-overexpressing tumors and increases the sensitivity of cancer cells to anti-PD-1 therapy.Glioblastoma-derived Kyn activates the AhR in TAMs, promoting several mechanisms that drive tumor progression." (PMID 39905317, 2025). "Our results emphasize the significance of depressing the IDO1-Kyn-AhR axis to activate ferroptosis signaling in the central nervous system as a therapeutic strategy to delay glioblastoma progression." (PMID 39863603, 2025). "Our study aimed to examine the expression of the key KP proteins TDO2, IDO1/2 and AhR, in newly diagnosed glioblastoma patients and their correlation with survival." (PMID 38951170, 2024). "In glioblastoma, macrophage-derived kynurenine suppressed T cell-mediated immunity, and macrophage-specific deletion of AhR in an intracranial glioblastoma mouse model reduced tumor growth." (PMID 38339226, 2024). "The present study aimed to investigate the expression of IDO1/2, TDO2, and AhR in glioblastoma tissues of newly diagnosed patients." (PMID 38951170, 2024). "We examined IL4I1, IDO1, and AHR expression in the TCGA database and their contribution to glioblastoma and low-grade glioma (LGG) clinical outcome." (PMID 38937431, 2024). "Kynurenine responsible for activating AhR in glioblastoma cells to increase Pol κ has been shown to result from TDO2 activity, as it is prevented by the selective TDO2 inhibitor 680C91." (PMID 39048947, 2024). "In the context of malignant gliomas, including glioblastoma, some groups have described AhR as a tumor promoter, while others have shown that AhR acts as a tumor suppressor." (PMID 38807762, 2024). "I3P was previously shown to perform growth-promoting functions via the ability to bind to and drive the nuclear translocation of the transcription factor AHR in glioblastoma cells." (PMID 38769298, 2024). "AhR drives CD39 and CD155 expression in tumor-associated macrophages, thereby impairing T cell response in glioblastoma." (PMID 38807762, 2024). "KYN binds to the aryl hydrocarbon receptor (AhR) and promotes cancer cell survival and motility in human glioblastoma cells and breast and ovarian cancer cells." (PMID 39311710, 2024).
glioblastoma (continued). "Actually, factors secreted by glioblastoma cells activate aryl hydrocarbon receptor (AHR) in TAMs; activation of AHR, in turn, enhances the expression of the Krüppel-like factor 4 (KLF4), and suppresses NF-κB signaling by TAMs." (PMID 39194524, 2024). "The analysis of comcomitant IDO1/2, TDO2, AhR expression in glioblastoma and its relationship with the tumour environment potentially will help to elucidate this interplay." (PMID 38951170, 2024). "In patient-derived glioblastoma cells, the deletion of AhR resulted in enhanced xenograft growth, invasion, and the expression of migratory genes." (PMID 37106727, 2023). "Glioblastoma cells produce kynurenine, which plays a role by stimulating aryl hydrocarbon receptor (AHR) in TAMs, which then contributes to the recruitment of TAMs via upregulated CCR2 expression." (PMID 37012233, 2023). "Activating the AHR pathway triggering tumor cell proliferation in astrocytoma, medulloblastoma, and glioblastoma (GBM)." (PMID 36003766, 2022). "Analysis of scRNA-seq data was used to detect the presence of Trp metabolism and AHR activity in different cell types in glioblastoma." (PMID 34646367, 2021). "As a promising naturally derived AhR agonist, rutaecarpine was proposed as a potential candidate for developing drugs against glioblastoma migration, particularly those with high AhR expression." (PMID 34955744, 2021). "Analysis of scRNA-seq data revealed that genes involved in Trp metabolism were expressed in almost all the cell types in glioblastoma and that most cell types, in particular macrophages and T cells, exhibited AHR activation." (PMID 34646367, 2021). "Given the importance of AhR in rutaecarpine-induced effects in U87 cells, if this compound has similar anti-migratory effects in the glioblastoma cells expressing less AhR is still unclear." (PMID 34955744, 2021). "TDO2 stimulates tumor development through kynurenine-aryl hydrocarbon receptor (AhR) axis in glioblastoma." (PMID 34174844, 2021). "Recently, emerging evidence has shown that the migration ability of glioblastoma cells was inhibited upon the activation of aryl hydrocarbon receptor (AhR), suggesting potential anti-tumor effects of AhR agonists." (PMID 34955744, 2021). "In our research, we found that rutaecarpine, but not evodiamine and dehydroevodiamine, can upregulate the expression of IL24 by activating the AhR signaling pathway, thereby inhibiting the migration of glioblastoma." (PMID 34955744, 2021). "Taken together, Trp metabolism and AHR activation are enriched in most cell populations present in glioblastoma tissue, with a particularly pronounced AHR activation in immune cells." (PMID 34646367, 2021). "Confirming and expanding the results of others and us 25, 29, 88, we found that in addition to Trp metabolism also AHR activity is highest in the mesenchymal subtype of glioblastoma." (PMID 34646367, 2021). "Such a positive correlation between the expression of AhR and the migration ability of glioblastoma cells was also found upon the activation AhR signaling pathway, in which the cell migration ability was decreased with a reduction in AhR mRNA expression." (PMID 34955744, 2021). "On the other hand, in terms of the constitutive expression of AhR, we also demonstrated that glioblastoma cells with higher constitutive AhR expression had higher migration ability." (PMID 34955744, 2021). "AHR activity in glioblastoma was upregulated particularly in macrophages and T cells, but to a lesser extent also in oligodendrocytes and all but two malignant cell clusters." (PMID 34646367, 2021). "NFkB plays an important role in the invasion of glioblastoma cells and there is also evidence that the AhR suppresses NFkB." (PMID 32731514, 2020).